ENSG00000285329 (novel protein)
Gene: Protein-coding gene on chromosome 16 (3,365,099 to 3,479,550, forward strand). Ensembl gene ENSG00000285329.
Genetic constraint (gnomAD): Missense variants: 144 observed, 115.93 expected, observed/expected ratio (o/e) 1.24, 90% interval 1.08 to 1.43. Synonymous variants: 54 observed, 43.25 expected, observed/expected ratio (o/e) 1.25, 90% interval 1 to 1.57.